TRBV5-4 (T cell receptor beta variable 5-4)
Description:
V region of the variable domain of T cell receptor (TR) beta chain that participates in the antigen recognition. Alpha-beta T cell receptors are antigen specific receptors which are essential to the immune response and are present on the cell surface of T lymphocytes. Recognize peptide-major histocompatibility (MH) (pMH) complexes that are displayed by antigen presenting cells (APC), a prerequisite for efficient T cell adaptive immunity against pathogens. Binding of alpha-beta TR to pMH complex initiates TR-CD3 clustering on the cell surface and intracellular activation of LCK that phosphorylates the ITAM motifs of CD3G, CD3D, CD3E and CD247 enabling the recruitment of ZAP70. In turn ZAP70 phosphorylates LAT, which recruits numerous signaling molecules to form the LAT signalosome. The LAT signalosome propagates signal branching to three major signaling pathways, the calcium, the mitogen-activated protein kinase (MAPK) kinase and the nuclear factor NF-kappa-B (NF-kB) pathways, leading to the mobilization of transcription factors that are critical for gene expression and essential for T cell growth and differentiation. The T cell repertoire is generated in the thymus, by V-(D)-J rearrangement. This repertoire is then shaped by intrathymic selection events to generate a peripheral T cell pool of self-MH restricted, non-autoaggressive T cells. Post-thymic interaction of alpha-beta TR with the pMH complexes shapes TR structural and functional avidity.
Synonyms: TRBV54; TCRBV5S4; TCRBV5S6A3N2T
Gene: T-cell receptor variable (V) gene on chromosome 7 (142,462,916 to 142,463,581, forward strand). Ensembl gene ENSG00000230099.
Subcellular location: Cell membrane
Gene Ontology:
Biological process: cell surface receptor signaling pathway
Cellular component: plasma membrane
Homologues: Paralogues in human: TRBV5-6 (89% identical), TRBV5-5 (85% identical), TRBV5-7 (82% identical), TRBV5-3 (77% identical), TRBV5-1 (69% identical), TRBV9 (60% identical), TRBV13 (54% identical), TRBV7-9 (48% identical), TRBV11-2 (47% identical), TRBV11-3 (46% identical), TRBV7-7 (46% identical), TRBV11-1 (46% identical), and 39 more.